PTH (parathyroid hormone)
Diseases named in the same sentence as PTH in open-access papers (continued):
Sharing a sentence is not in itself a finding about the gene and the disease.
Hypercalcemia (continued). "The excess of PTH leads to hypercalcemia through the following mechanisms: increased intestinal calcium absorption, increased tubular calcium reabsorption, and increased bone reabsorption." (PMID 32720971, 2020). "The maintenance of elevated parathormone (PTH) levels leads to hypercalcemia, hypophosphatemia, and reduced bone mass with increased risk of fractures, as well as vascular calcification, with an increased risk of cardiovascular events and graft dysfunction." (PMID 32720971, 2020). "Due to its clinical context (severe hypercalcemia and very high levels of PTH), parathyroid carcinoma (PC) was suspected although imaging studies were not characteristic." (PMID 32292610, 2020). "The presence of hypercalcemia with suppressed PTH and inappropriately elevated 1,25(OH)2D suggests a diagnosis of granulomatous disease." (PMID 31687644, 2019). "Some studies investigated several predisposing factors for PTC in PHPT, such as the tumor promoting effect of PTH, the goitrogenic effect and increased mitotic activity induced by hypercalcemia and neck irradiation." (PMID 31311533, 2019). "It is important for clinicians to consider PJP as an etiology of granulomatous pneumonia and non-parathyroid hormone mediated hypercalcemia in chronically immunosuppressed organ transplant recipients for timely diagnosis and management." (PMID 31438872, 2019). "Primary hyperparathyroidism (PHPT) is characterized by hypercalcemia with elevated or inappropriately normal serum PTH levels." (PMID 31844831, 2019). "Laboratory investigations revealed hypercalcemia (total/ionized 199.5/101.75 mg/L), normal serum phosphorus (40.20 mg/L), and a low intact parathyroid hormone (9.70 pg/ml)." (PMID 31594542, 2019). "Zoledronic acid can temporarily decrease PTH‐dependent hypercalcemia and is not only used in the treatment of osteoporosis because of its anti‐bone‐resorptive effects but also for the treatment of bone metastases, usually given in 4‐week intervals." (PMID 31044184, 2019). "Primary hyperparathyroidism with normal PTH is rare but physicians should be aware of this possibility in patients with hypercalcaemia." (PMID 31074404, 2019). "Cinacalcet wasprescribed based on the following findings: persistent hyperphosphatemia (15patients); recurrent hypercalcemia (6 patients); and persistent hyperphosphatemia +recurrent hypercalcemia (5 patients) accompanied by PTH levels > 600 pg/mL." (PMID 31419274, 2019). "She had recurrent structural and biochemical disease, with evidence of hypercalcemia and elevated PTH levels, as well as right recurrent laryngeal nerve palsy and lung metastasis." (PMID 31708875, 2019). "Since 1976, approximately 140 cases of hypercalcemia and normal PTH levels due to parathyroid adenoma have been reported in the literature." (PMID 31074404, 2019). "Inactivating mutations of the CaSR gene reduce the receptor sensitivity to Ca resulting in increased PTH secretion, reduced renal calcium excretion, and hypercalcaemia." (PMID 32120468, 2019). "Given the patient's history of long-term dialysis, bone pain, high levels of intact parathyroid hormone(i-PTH) and hypercalcemia, we performed ultrasonography which showed solid nodules in the bilateral parathyroid glands." (PMID 31764770, 2019). "Primary hyperparathyroidism (PHPT) is characterized by hypercalcemia and elevated parathyroid hormone (PTH) concentrations." (PMID 31068134, 2019). "Case 1: A 62-year-old man was hospitalized for left-sided palpable neck mass, hypercalcemia and elevated PTH." (PMID 31142320, 2019). "The presence of hypercalcemia and accompanying low PTH raised the concern for malignancy, while the depressed TSH indicated hyperthyroidism." (PMID 31641565, 2019). "Patient #5 was in remission for 22 months following parathyroidectomy, but reappearance of symptomatic hypercalcemia and elevated PTH levels led to the detection of recurrent disease." (PMID 31708875, 2019).
Hypercalcemia (continued). "The phenotype change is initiated by hyperphosphatemia, hypercalcemia, and, possibly, high concentrations of parathyroid hormone (PTH)." (PMID 30970562, 2019). "Hypercalcemia crisis is a complex disorder rarely induced by tertiary hyperparathyroidism, which clinically presents as nonsuppressible parathyroid hyperplasia with persistent increased PTH levels and hypercalcemia." (PMID 31088386, 2019). "Pathology revealed an intrathyroidal 2.7 cm parathyroid carcinoma and metastatic carcinoma in 2 left neck lymph nodes, PTH decreased after the surgery but remained elevated, with hypercalcemia and hypophosphatemia." (PMID 31708875, 2019). "The majority of the patients (n=43, 58.1%) had severe hypercalcemia (>14 mg/dL), normal phosphate values in 55/69 (79.7%) cases with available data and suppressed PTH in 51/65 (78.4%) cases with available data." (PMID 30396880, 2019). "Cinacalcet, a calcimimetic, is an allosteric modulator of the CaSR that efficiently decreases hypercalcemia in PTH‐dependent disease." (PMID 31044184, 2019). "Subsequent laboratory investigations detected hypercalcemia (2.8 mmol/L), hypophosphatemia (0.69 mmol/L) and parathyroid hormone (PTH) (15 pmol/L)." (PMID 31039511, 2019). "Hypercalcemia and elevated PTH are hallmarks of PHPT, in agreement with our review where all cases had elevated calcium and PTH laboratory values." (PMID 31722742, 2019). "In the only other case of symptomatic hypercalcemia described previously, also in a pediatric patient, the hypercalcemia was preceded by hypophosphatemia and increased serum PTH upon initiation of therapy." (PMID 31687646, 2019). "Based on knowledge from other NHLs, hypercalcemia would result from increased 1.25(OH)2D3 and/or PTH-rp activity." (PMID 31594542, 2019). "Primary hyperparathyroidism (PHPT) is a disease that excessively secretes parathyroid hormone (PTH) and causes osteoporosis, ureteral stone, and hypercalcemia." (PMID 31727048, 2019). "PHP with normal PTH is rare but physicians should be aware of this possibility in patients with hypercalcemia." (PMID 31074404, 2019). "Patients with ESRD diagnosed with SHPT and having hypercalcemia, hyperphosphatemia, and high levels of i-PTH are suitable candidates for this procedure." (PMID 31764770, 2019). "Aside severe renal failure and hypercalcemia, laboratory tests showed hypophosphataemia (0.55 mg/dL, n.v. = 2.5–4.50 mg/dL) and high PTH (919.0 p/mL; n.v.: 6.4–52 pg/mL)." (PMID 31142320, 2019). "Investigations revealed hypercalcemia with elevated parathyroid hormone and an asymptomatic kidney stone." (PMID 31722742, 2019). "Hypercalcemia persisted nonetheless, and 1 month later S‐Ca‐ion was 1.46 mmol/L, PTH 613 ng/L, and ALP 476 U/L." (PMID 31044184, 2019). "Biochemical assessment of the index case confirmed the diagnosis of hyperparathyroidism with severe hypercalcemia (serum Caalb adj = 14.9 mg/dL, nr = 8.4–10.2 mg/dL; PTH = 703 pg/mL, nr = 15–65 pg/mL)." (PMID 29755684, 2018). "Teriparatide, a parathyroid hormone analogue, can increase trabecular bone mass but has side effects such as concurrent stimulation of bone resorption and potential hypercalcemia (Dede, Makras, & Anastasilakis, 2017; Fukumoto & Matsumoto, 2017)." (PMID 29210174, 2018). "Accordingly, female gender, hypercalcemia and elevated PTH level are common factors in the pathogenesis of gallstones in PHPT and SHPT treated with vitamin D and Ca-containing phosphate binders." (PMID 29301445, 2018). "“Symptomatic hypervitaminosis D” or “vitamin D intoxication” is recognized by markedly elevated 25(OH)D concentration (usually >150 ng/ml) that coincides with normal or slightly increased 1,25(OH)2D, hypercalcemia, hypercalciuria and suppressed PTH." (PMID 29904370, 2018). "Hypercalcemia investigation revealed intact PTH 19 pg/mL (16-87 pg/mL), 25-OH vitamin D 15.7 ng/mL (>30 ng/mL), and PTH-related peptide (PTHrP) 63.4 pmol/L (<2.3 pmol/L)." (PMID 29755405, 2018).
Hypercalcemia (continued). "Laboratory analysis showed a hypercalcemia: 13.4 mg/dl (normal range: 8.6–10.4) and plasma PTH was 398 pg/ml (normal range: 8–76 pg/ml), 24-hour urinary calcium was at 328 mg/24 h (N < 300)." (PMID 30317121, 2018). "We report a case of hypercalcemia with suppressed parathyroid hormone (PTH) levels necessitating treatment with bisphosphonates during pregnancy." (PMID 29694631, 2018). "In clinical practice, concerns about hypercalcemia and potential vascular calcification have confined treatment of vitamin D in patients with elevated PTH and with relatively low calcium levels." (PMID 30400889, 2018). "In most cases, an incidental finding of hypercalcemia seems to have been the reason for the analysis of PTH." (PMID 29532143, 2018). "The patient’s parathyroid hormone levels remained high (> 1500 ng/l) and he developed hypercalcemia after the start of chronic dialysis." (PMID 29751781, 2018). "Abrupt discontinuation of cinacalcet post-transplantation coupled with high PTH and vitamin D levels can lead to acute, severe hypercalcemia." (PMID 30109232, 2018). "Even though hypercalcemia is multifactorial, most patients have inappropriately high PTH level for the degree of hypercalcemia." (PMID 30109232, 2018). "A recent global consensus statement on nutritional rickets defines vitamin D toxicity as hypercalcaemia and 25(OH)D >250 nmol/L with hypercalciuria and suppressed PTH." (PMID 29533998, 2018). "Three months later, she developed severe hypercalcemia with normal 25-OH vitamin D and parathyroid hormone levels and high 1,25-dihydroxyvitamin D levels." (PMID 30290590, 2018). "Recurrence is defined as recurrent hypercalcemia with inappropriately normal or elevated serum intact PTH 6 months after surgery, when normocalcemia and normal intact PTH levels had been achieved post-operatively." (PMID 30459713, 2018). "We add our experience in evaluating hypercalcemia with decreased PTH levels and the use of bisphosphonates during pregnancy with good results." (PMID 29694631, 2018). "The longer time on HD, hypercalcemia, hyperphosphatemia and elevated parathyroid hormone level were observed in the HD patients with cinacalcet." (PMID 29301445, 2018). "If hypercalcemia persists despite these measures, and if PTH level is persistently high, cinacalcet can be started temporarily and dose titrated." (PMID 30109232, 2018). "We report a case of hypercalcemia with suppressed PTH levels necessitating treatment with bisphosphonates during pregnancy." (PMID 29694631, 2018). "NSHPT is often discovered during the first days of life because of severe, symptomatic, PTH-dependent hypercalcemia, polyuria, dehydration, hypotonia, bone changes and failure to thrive." (PMID 30376845, 2018). "Exogenous VDT due to vitamin D overdosing is diagnosed by markedly elevated 25(OH)D concentrations (>150 ng/ml) accompanied by severe hypercalcemia and hypercalciuria and by very low or undetectable parathyroid hormone (PTH) activity." (PMID 30294301, 2018). "As part of the workup for his hypercalcemia, blood samples were sent for evaluation including vitamin D and parathyroid hormone (PTH) levels." (PMID 29673407, 2018). "Examinations revealed hypercalcemia (14.3 mg/dL) with an increased level of intact parathyroid hormone (iPTH) (361 pg/mL)." (PMID 29734949, 2018). "The overproduction of PTH leads to hypercalcemia and hypocalciuria due both to significant calcium release from bones and increase of renal calcium reabsorption." (PMID 30376845, 2018). "Preoperative symptoms were alleviated, and the serum PTH and alkaline phosphatase levels, hyperphosphatemia, and hypercalcemia were improved or normalized in all 6 patients." (PMID 30294428, 2018). "Laboratory tests showed hypercalcaemia 4.1 mmol/l, hyperparathyroidism with very high parathyroid hormone (PTH) value (1088 pg/ml or 13 times normal)." (PMID 28819506, 2017).
Hypercalcemia (continued). "PTHrP induces hypercalcemia in a parathyroid hormone (PTH)-like manner by binding to and activating the common PTH/PTHrP (PTH1) receptor at the surface of renal tubular epithelial cells and osteoblasts." (PMID 29056680, 2017). "A pretreatment biopsy specimen showed strong cytoplasmic immunoreactivity to anti-PTH-rP antibody, suggesting that overproduction of PTH-rP accounted for the hypercalcemia." (PMID 28894614, 2017). "FHH2 is characterized by hypercalcemia, inappropriately normal or raised parathyroid hormone (PTH) concentrations, and normal or low urinary calcium excretion." (PMID 29046478, 2017). "K/DOQI guidelines recommend that patients with severe hyperparathyroidism (persistent serum levels of intact PTH >800 pg/mL [88.0 pmol/L]), accompanied with hypercalcemia and/or hyperphosphatemia refractory to medical therapy should receive PTX." (PMID 28853301, 2017). "Laboratory findings include decreased TRP, hypophosphatemia, hypercalcemia, elevated serum 1,25(OH)2D, decreased serum PTH, hypercalciuria and nephrocalcinosis." (PMID 29280738, 2017). "We report a case of severe and complicated PTH-independent hypercalcemia in a symptomatic 3-year-old boy." (PMID 29181374, 2017). "Hypercalcemia improved with pamidronate treatment, but her plasma PTH remained high despite vitamin D supplementation." (PMID 29183364, 2017). "A recent meta-analysis of CKD in patients who were not undergoing treatment with HD also indicates the efficacy of paricalcitol in lowering PTH levels, but with reference to a careful use of vitamin D analogues because of hypercalcemia and calcification risks." (PMID 28956807, 2017). "During treatment, levels of serum calcium increased significantly (p < 0.05), three OA patients (1.71%) developed hypercalcemia (Ca > 10.5 mg/dL) and PTH decreased significantly (p < 0.05) after vitamin D2 supplementation." (PMID 28933742, 2017). "In a previous report, 82% of cats with neoplasia and hypercalcemia were due to PTH-independent mechanisms, and circulating PTHrP was increased in the majority of cases." (PMID 29056680, 2017). "Blood tests revealed hypercalcemia (13.8 mg/dl; normal range, 8.6 to 10.2 mg/dl), elevated PTH levels (305 pg/ml; normal range, 10 to 70 pg/ml), and concomitant low levels of 25-hydroxyvitamin D (25-OH vitamin D)." (PMID 29183364, 2017). "Classically, the clinical features of parathyroid carcinoma include hypercalcemia, palpable neck mass, high serum PTH, and osteitis fibrosa cystica." (PMID 29047366, 2017). "Similar to the majority of reported cases, both hypercalcemia and a high level of parathyroid hormone were observed in the present patient." (PMID 28482911, 2017). "As in our case, we suggest further evaluation (e.g. parathyroid gland imaging) of children, especially adolescents, with unexplained hypercalcemia despite a normal PTH level." (PMID 28443817, 2017). "In group 2, five infants of ages ranging between 15 days to 8 months had presented with mild hypercalcemia, low serum PTH, normal serum 25OHD, and increased urinary calcium/creatinine ratio." (PMID 28443817, 2017). "Most PCs secrete parathyroid hormone (PTH) resulting in hypercalcemia, however, approximately 40 PC cases have been reported in which there was no increase in PTH production and morbidity resulted from tumor invasion and spread." (PMID 28881068, 2017). "When hypercalcemia recurred after the fourth chemotherapy cycle, cinacalcet monotherapy induced a consistent decline in PTH-rp levels, thus preventing a further increase in serum calcium levels." (PMID 28977163, 2017). "On the other hand, we defined 7 cases of PTH-dependent hypercalcemia, constituting 35% of our series." (PMID 28443817, 2017). "One patient with acute lymphoblastic leukemia displayed moderate hypercalcemia, low serum PTH (10 pg/mL), normal serum 25OHD, PTHrP, and renal function tests." (PMID 28443817, 2017).
Hypercalcemia (continued). "The mechanism through which cinacalcet improved PTH-rp mediated hypercalcemia is still unclear, but studies have suggested that a potential mechanism is the activation of calcitonin secretion." (PMID 28977163, 2017). "Laboratory findings include decreased TRP, hypophosphatemia, hypercalcemia, elevated 1,25(OH)2D, suppressed PTH, hypercalciuria, nephrocalcinosis, hyperuricosuria and low-molecular-weight proteinuria." (PMID 29280738, 2017). "A previous report described a 57-year-old male with hypercalcemia and a pulmonary tumor secreting PTH-rp." (PMID 28977163, 2017). "The patient subsequently developed liver metastasis and hypercalcemia with high 1,25 OH vitamin D and suppressed parathyroid hormone (PTH) levels." (PMID 28977163, 2017). "In PHPT, PTH hypersecretion due to tumor parathyroid cell proliferation induces hypercalcemia by increasing calcium mobilization from bone and calcium reabsorption from kidney." (PMID 28157158, 2017). "She had hypercalcemia and elevated parathyroid hormone levels suggesting primary hyperparathyroidism." (PMID 29183364, 2017). "Adequate vitamin D supplementation resulted in worsening of hypercalcemia and failure of reduction in PTH levels." (PMID 28732535, 2017). "The classical symptoms and signs of PHPT reflect the combined effects of increased PTH secretion and hypercalcemia." (PMID 28900835, 2017). "Considering PCA in the differential diagnosis of hypercalcemia due to raised PTH is of utmost importance because complete resection of the tumor is essential at the time of the initial diagnosis else it would lead to substantial morbidity and mortality." (PMID 29354025, 2017). "Because the PTH in this case was “inappropriately high” for the severe hypercalcemia, tertiary hyperparathyroidism was considered in the differential diagnosis." (PMID 27683096, 2016). "For example, a β-arrestin–biased ligand, PTH (parathyroid hormone), promotes bone formation and homeostasis, thus reducing hypercalcemia of malignancy and osteoporosis." (PMID 27529230, 2016). "Patients with GPA have higher mean preoperative PTH and serum calcium levels but are less likely to have symptoms of hypercalcemia." (PMID 27756436, 2016). "At delivery, she was diagnosed with hypercalcemia with an inappropriately normal PTH and a CCCR of 2.67%, which fell to 0.88% during lactation." (PMID 27957351, 2016). "FHH is an autosomal dominant disease characterized by mild hypercalcemia, very low urine calcium excretion, and elevated serum PTH." (PMID 27508075, 2016). "The decrease in PTH, which has been previously documented in animals with vitamin D toxicosis, is likely secondary to hypercalcemia and to the inhibitory effects of vitamin D metabolites on PTH production by the parathyroid glands." (PMID 27243456, 2016). "Nutritional vitamin D supplementation is used for additional local parathyroid (PTH) suppression, with lower incidence of hypercalcemia and hyperphosphatemia." (PMID 27827962, 2016). "We describe a 65‐year‐old woman who had hypercalcemia with normal circulating parathyroid hormone concentrations and hypocalciuria, features consistent with FHH, but she did not have CaSR and AP2σ mutations." (PMID 26729423, 2016). "Previous studies have suggested increased PTH degradation within the glands in the presence of hypercalcemia and, consequently, a higher proportion of PTH fragments in the circulation." (PMID 27812604, 2016). "On biochemical investigations, the present case showed hypercalcemia and hyperphosphatemia, along with increased parathyroid hormone level which aided in the confirmatory diagnosis." (PMID 27974979, 2016). "Small brain size was associated with a reduced number of cells and proliferation rates, but deletion of the parathyroid hormone (Pth) gene, which corrects hyperparathyroidism, hypercalcemia, and hypophosphatemia, normalized these alterations." (PMID 27242543, 2016).